MIR320D1 (microRNA 320d-1)
Synonyms: hsa-mir-320d-1; formerly MIRN320D1
Gene: MicroRNA gene on chromosome 13 (40,727,828 to 40,727,875, reverse strand). Ensembl gene ENSG00000211491.
Gene Ontology:
Biological process: cellular response to glucose stimulus; long-term synaptic potentiation; miRNA-mediated post-transcriptional gene silencing; negative regulation of gene expression; positive regulation of stem cell proliferation
Cellular component: RISC complex